Y_RNA (Y RNA )
Gene: Miscellaneous RNA gene on chromosome 20 (30,309,015 to 30,309,126, reverse strand). Ensembl gene ENSG00000200325.
Homologues: Orthologues: chimpanzee Y_RNA (96% identical), macaque Y_RNA (88% identical). Paralogues in human: Y_RNA (97% identical), Y_RNA (96% identical), Y_RNA (92% identical), Y_RNA (87% identical), RNY1P5 (84% identical), Y_RNA (84% identical), Y_RNA (83% identical), Y_RNA (82% identical), Y_RNA (81% identical), RNY1 (80% identical), RNY1P1 (80% identical), Y_RNA (80% identical), and 97 more.